DDX11L1 (DEAD/H-box helicase 11 like 1 (pseudogene))
Gene: Transcribed unprocessed pseudogene on chromosome 1 (12,010 to 13,670, forward strand). Ensembl gene ENSG00000223972.
Diseases named in the same sentence as DDX11L1 in open-access papers:
DDX11L1 is named in the same sentence as 1 disease in open-access papers, as found by Europe PMC text mining. Sharing a sentence is not in itself a finding about the gene and the disease. The quoted sentences say what the papers report.
tumour (2 papers, 2022 to 2024). "Significant African-ancestry-specific findings include an elevated tumour mutational burden, increased percentage of genome alteration, a greater number of predicted damaging mutations and a higher total of mutational signatures, and the driver genes NCOA2, STK19, DDX11L1, PCAT1 and SETBP1." (PMID 36045292, 2022).